RGMA (repulsive guidance molecule BMP co-receptor a)
Description:
Member of the repulsive guidance molecule (RGM) family that performs several functions in the developing and adult nervous system. Regulates cephalic neural tube closure, inhibits neurite outgrowth and cortical neuron branching, and the formation of mature synapses. Binding to its receptor NEO1/neogenin induces activation of RHOA-ROCK1/Rho-kinase signaling pathway through UNC5B-ARHGEF12/LARG-PTK2/FAK1 cascade, leading to collapse of the neuronal growth cone and neurite outgrowth inhibition. Furthermore, RGMA binding to NEO1/neogenin leads to HRAS inactivation by influencing HRAS-PTK2/FAK1-AKT1 pathway. It also functions as a bone morphogenetic protein (BMP) coreceptor that may signal through SMAD1, SMAD5, and SMAD8.
Synonyms: RGM
Tractability: Antibody: a drug acting on it is in phase 2 or 3 trials; UniProt places it where antibodies can reach, with medium confidence; UniProt predicts a signal peptide or a membrane-spanning region; its Gene Ontology location is reachable by antibodies, with medium confidence. PROTAC: its protein half-life has been measured.
Gene: Protein-coding gene on chromosome 15 (93,035,271 to 93,089,211, reverse strand). Ensembl gene ENSG00000182175.
Subcellular location: Cell membrane
Subcellular location (Human Protein Atlas): Nucleoplasm; Cytosol; Predicted to be secreted
Pathways (Reactome):
Developmental Biology: Netrin-1 signaling
Gene Ontology:
Molecular function: protein binding; transferrin receptor binding; coreceptor activity; signaling receptor binding
Biological process: positive regulation of transcription by RNA polymerase II; BMP signaling pathway; negative regulation of axon regeneration; negative regulation of collateral sprouting; negative regulation of neuron projection development; positive regulation of neuron projection development
Cellular component: endoplasmic reticulum; plasma membrane; cell surface
Genetic constraint (gnomAD): Loss-of-function variants: 11 observed, 21.03 expected, observed/expected ratio (o/e) 0.52, 90% interval 0.33 to 0.87. The upper end of that interval is the gene's LOEUF score, 0.87, which puts it in group 3 of 6, group 1 being the genes least tolerant of losing a copy. Missense variants: 547 observed, 601.06 expected, observed/expected ratio (o/e) 0.91, 90% interval 0.85 to 0.98. Synonymous variants: 308 observed, 264.91 expected, observed/expected ratio (o/e) 1.16, 90% interval 1.06 to 1.28.
Homologues: Orthologues: chimpanzee RGMA (99% identical), macaque RGMA (93% identical), pig RGMA (93% identical), mouse Rgma (92% identical), rat Rgma (92% identical), guinea pig RGMA (92% identical), tropical clawed frog rgma (74% identical), zebrafish rgma (64% identical), rabbit RGMA (62% identical), Caenorhabditis elegans drag-1 (24% identical). Paralogues in human: RGMB (47% identical), HJV (44% identical).
Diseases named in the same sentence as RGMA in open-access papers:
RGMA is named in the same sentence as 55 diseases in open-access papers, as found by Europe PMC text mining. Sharing a sentence is not in itself a finding about the gene and the disease. The quoted sentences say what the papers report.
breast carcinoma (9 papers, 2019 to 2025). "Downregulation of RGMA is reported in colorectal and breast cancer and has been associated with cancer progression and poor prognosis." (PMID 31827134, 2019). "CACNA1B, CDCA8, and RGMA were identified as prognostic factors and a promising therapeutical target in breast cancer." (PMID 40665355, 2025). "RGMA acts as a tumor suppressor gene in colorectal cancer, breast cancer, prostate cancer, lymphoma and other tumors." (PMID 37308925, 2023). "miR-4472 levels were reduced, and repulsive guidance molecule A (RGMA) mRNA or protein levels were increased after overexpression of RP11-551L14.4 in the breast cancer cells." (PMID 36523479, 2022). "Another example is repulsive guidance molecule member A (RGMA), which is a gene in a prognostic mRNA signature for breast cancer whose methylation frequency can be used in evaluating colon cancer prognosis." (PMID 35677637, 2022). "Correlation analysis between RP11-551L14.4 and RGMA mRNA expression in breast cancer tissues revealed a positive relationship." (PMID 36523479, 2022). "In fact, overexpression of RGMA has been shown to decrease breast cancer in humans." (PMID 40004168, 2025). "Interestingly, eight genes (ID4, LTBP4, GPM6B, RGMA, EFCAB1, ALX4, OSR1 and PPARA) were confirmed to be down-expressed in breast cancer tissues, and associated with the overall survival time of breast cancer patients, as high expression of these genes correlate with an improved prognosis." (PMID 32650755, 2020). "Subsequently, we further narrowed down the eight candidate genes (TRIM47, SPHK1, RGMA, ROPN1B, LARP6, ROPN1, NPM2 and LPL) that are shared in TNBC compared to ER+ and HER2+ breast cancer subtypes in cancer cells." (PMID 40635123, 2025). "The potential target genes of miR-1908-3p in breast cancer included ID4, LTBP4, GPM6B, RGMA, EFCAB1, ALX4, OSR1 and PPARA." (PMID 32650755, 2020). "Based on these findings, a potential miR-1908-3p-mRNA regulatory network, miR-1908-3P-ID4/ LTBP4/ GPM6B/ RGMA/ EFCAB1/ ALX4/ OSR1/ PPARA, contributing to breast cancer onset and progression could be established." (PMID 32650755, 2020). "RGMA is known to be a tumor suppressor gene, not specific to breast cancer." (PMID 40004168, 2025).
epilepsy (7 papers, 2014 to 2025). A brain disorder characterized by episodes of abnormally increased neuronal discharge resulting in transient episodes of sensory or motor neurological dysfunction, or psychic dysfunction. "RGMa’s role extends to epilepsy, where its downregulation has been linked to mossy fiber sprouting and neuroinflammation." (PMID 40244061, 2025). "RGMa is implicated in epilepsy, with its downregulation linked to mossy fiber sprouting, neuroinflammation, and microglial activation." (PMID 40244061, 2025). "Therefore, we selected miR‐20a‐5p as a candidate regulator of RGMa expression in a PTZ‐induced epilepsy model." (PMID 32779334, 2020). "Deletions affecting this gene are very rare, and, so far, there is only one case report of a child with global developmental delay, epilepsy and ASD who was found to have a de novo deletion encompassing the RGMA and CHD2 genes." (PMID 24834135, 2014). "Here, we reveal that the miR‐20a‐5p‐RGMa‐RhoA pathway regulates axonal growth and neuronal branching in vitro and that silencing miR‐20a‐5p regulates epileptogenesis through RGMa‐RhoA‐mediated synaptic plasticity in a PTZ‐induced epilepsy model." (PMID 32779334, 2020). "Interestingly, a clinical case with moderate intellectual disability, epilepsy, and truncal obesity, suspected of PWS, showed a 15q26.1 microdeletion encompassing two genes: Chromodomain helicase DNA-binding protein 2 (CHD2) and RGMA." (PMID 39407757, 2024). "Furthermore, in primary hippocampal neurons, the miR‐20a‐5p‐RGMa‐RhoA pathway regulated axonal growth and neuronal branching; in the PTZ‐induced epilepsy model, silencing miR‐20a‐5p prevented epileptogenesis through RGMa‐RhoA‐mediated synaptic plasticity but did not change MFS." (PMID 32779334, 2020).
Stroke (6 papers, 2015 to 2025). Sudden impairment of blood flow to a part of the brain due to occlusion or rupture of an artery to the brain. "The critical role of the neogenin and RGMa pathway in neuronal death following stroke has been proven with various experiments." (PMID 40244061, 2025). "Hence, an artificial nanoplatform loaded with anti‐Repulsive Guidance Molecule a monoclonal antibody (anti‐RGMa) and coated with microglia membrane (MiCM) is reported for stroke treatment, namely MiCM@PLGA/anti‐RGMa/Fe3O4@PFH (MiCM‐NPs)." (PMID 39475454, 2024). "Here, we demonstrated that RGMa is expressed in endothelial cells in EAE, which is consistent with our previous study on stroke." (PMID 35664003, 2022).
multiple sclerosis (5 papers, 2012 to 2025). A progressive autoimmune disorder affecting the central nervous system resulting in demyelination. "Beyond its role in the nervous system, RGMa is implicated in immune regulation, promoting helper T cell activation and is expressed on Th17 cells of patients with multiple sclerosis." (PMID 40305434, 2025). "Repulsive guidance molecule-a (RGMa) is involved in the pathogenesis of multiple sclerosis (MS), but its role needs to be further explored." (PMID 35664003, 2022). "Inhibition of RGMa attenuates pathological dysfunction in animal models of central nervous system (CNS) diseases including spinal cord injury, multiple sclerosis, and neuromyelitis optica." (PMID 33589594, 2021). "Accumulating studies in neurological diseases spinal cord injury (SCI) and multiple sclerosis (MS) demonstrate that increased expression of RGMa inhibits axon regeneration and functional recovery in the injured CNS3–6." (PMID 33589594, 2021). "In addition, RGMa is greatly expressed in CD4+ T cells in experimental autoimmune encephalomyelitis mice, an animal model of multiple sclerosis (MS), and therapeutic inhibition of RGMa improved the clinical symptoms of diseased mice." (PMID 37992159, 2023). "RGMa is a GPI-anchored membrane protein that exerts functions on axon guidance and axonal regeneration, which is involved in CNS diseases including ischemic cerebral infarction, multiple sclerosis, epilepsy, Parkinson’s disease, and spinal cord injury." (PMID 35664003, 2022).
experimental autoimmune encephalomyelitis (4 papers, 2018 to 2023). An autoimmune demyelinating disease of the central nervous system that is produced experimentally in animals by the injection of homogenized brain or spinal cord in Freund's adjuvant. "We previously showed RGMa contributes to pathogenesis of experimental autoimmune encephalomyelitis (EAE), an animal model of MS." (PMID 30333477, 2018). "In the case of MS, RGMa has been reported as upregulated in disease lesions, and in the experimental autoimmune encephalomyelitis (EAE) mouse model, anti-RGMa neutralizing antibody treatment was shown to attenuates motor symptoms by modulating T cell responses." (PMID 35784362, 2022). "We induced experimental autoimmune encephalomyelitis in nonobese diabetic mice (NOD-EAE mice) and treated them with humanized anti-RGMa monoclonal antibody." (PMID 30333477, 2018).
neuromyelitis optica (4 papers, 2018 to 2024). A rare inflammatory disease of the central nervous system characterized mainly by attacks of uni- or bilateral optic neuritis (ON) and acute myelitis. "In addition, RGMa may also be involved in neuromyelitis optica (NMO) as in an NMO animal model similar effects of anti-RGMa treatment were observed such as a more favourable disease course, a weaker immune response, and a partial restoration of AQP4 and GFAP reactivity." (PMID 33324887, 2019).
colon cancer (3 papers, 2012 to 2022). "Decreased PIGR expression has been found in colon tumours, while RGMA has been reported to have an inhibitory effect on cancer progression." (PMID 29642861, 2018). "Many of these actions depend on an interaction with neogenin, a homologue of the netrin receptor deleted in colon cancer, while the BMP signaling function of RGMA has not been clearly linked to its observed biologic actions." (PMID 23029472, 2012).
prostate carcinoma (3 papers, 2014 to 2023). A carcinoma that arises from epithelial cells of the prostate gland. "Contrary, RAR beta 2, ER alpha, PGR, and RGMA mRNA levels were decreased in prostate cancer tissue compared to normal one." (PMID 25535400, 2014). "According to the previous studies, results exhibited that, RGMA mRNA was decreased in the prostate cancer tissues compared to normal prostate tissues." (PMID 25535400, 2014). "Our investigations have also shown an increase of H3K27me3 on RGMA gene which would explain the silencing of this gene in prostate cancer." (PMID 25535400, 2014). "On the contrary, RAR beta 2, ER alpha, PGR, RGMA protein levels were notably reduced in prostate cancer tissues compared to normal tissues." (PMID 25535400, 2014). "In a comparative way, our studies showed that RGMA expression was down-regulated in most of the prostate cancer tissues and was positively correlated with Gleason score." (PMID 25535400, 2014). "Based on the overall results, we believe in a direct role of EZH2 in silencing of RAR beta 2, ER alpha, PGR, and RGMA genes via H3K27me3 mark in prostate cancer and therefore indicates adverse prognosis." (PMID 25535400, 2014). "The present study clearly pointed out H3K27me3 as an epigenetic mark involved in the silencing of RAR beta 2, ER alpha, PGR, and RGMA genes in prostate cancer." (PMID 25535400, 2014). "In this study, the focus will be on histone modifications and the primary objectives are to map H3K27me3 marks and quantify RAR beta 2, ER alpha, SRC3, RGMA, PGR, and EZH2 gene expressions in prostate cancer tissues compared to normal tissues." (PMID 25535400, 2014). "In fact, to study histone methylation, a selection of six genes involved in prostate cancer was made, including RAR beta 2, ER alpha, PGR, RGMA, EZH2, and SRC3." (PMID 25535400, 2014). "The study demonstrated that H3K27me3 level was significantly enriched at the RAR beta 2, ER alpha, PGR, and RGMA promoter regions in prostate cancer tissues compared to normal tissues." (PMID 25535400, 2014). "Also this study revealed that reverse correlation of RAR beta 2, ER alpha, PGR, and RGMA expressions with EZH2, SRC3, and AR expressions in prostate cancer tissues suggests that these genes are the target of EZH2." (PMID 25535400, 2014).
Cerebral ischemia (2 papers, 2022 to 2024). Restriction of arterial blood supply to the brain associated with insufficient oxygenation to support the metabolic requirements of the tissue. "There is experimental evidence that inhibition of RGMa in models of cerebral ischemia can lead to improved clinical outcome." (PMID 36456640, 2022).
ischemic stroke (2 papers, 2017). A stroke disorder caused by obstruction of blood flow to the brain, due to thrombotic (local blood clot formation) or embolic (due to a blood clot or other material traveling from another site) event. "Although RGMa expression levels are relatively low in the adult CNS, RGMa expression is induced following ischemic stroke in humans and spinal cord injury in rats." (PMID 29259705, 2017).
triple-negative breast carcinoma (2 papers, 2020 to 2021). An invasive breast carcinoma which is negative for expression of estrogen receptor (ER), progesterone receptor (PR), and human epidermal growth factor receptor 2 (HER2). "It was reported miR-135b-3p could inhibit cell clonogenicity and metastasis in triple-negative breast cancer by targeting RGMA." (PMID 33643915, 2020).
vascular dementia (2 papers, 2025). A degenerative vascular disorder affecting the brain. "In this study, we explored the involvement of RGMa and the therapeutic effects of an anti-RGMa neutralizing antibody in a mouse model of vascular dementia (VaD)." (PMID 39613526, 2025).
acute lymphoblastic leukemia (1 paper, 2025). Leukemia with an acute onset, characterized by the presence of lymphoblasts in the bone marrow and the peripheral blood. "To elucidate whether Tax could directly induce RGMA gene expression, we constructed a Tax-inducing lentiviral vector and integrated Tax-coding cDNA into Jurkat cells, a T cell acute lymphoblastic leukemia cell line." (PMID 40305434, 2025).
amyotrophic lateral sclerosis (1 paper, 2025). Amyotrophic lateral sclerosis (ALS) is a neurodegenerative disease characterized by progressive muscular paralysis reflecting degeneration of motor neurons in the primary motor cortex, corticospinal tracts, brainstem and spinal cord. "Amyotrophic lateral sclerosis (ALS) is characterized by the progressive degeneration of motor neurons, and RGMa’s role in axonal growth inhibition and inflammation suggests it may contribute to disease progression." (PMID 40244061, 2025).
brain injury (1 paper, 2024). Acute and chronic (see also brain INJURIES, CHRONIC) injuries to the brain, including the cerebral hemispheres, CEREBELLUM, and brain STEM. "Repulsive guidance molecule A (RGMa) is an inhibitor of neuronal growth and survival which is upregulated in the damaged central nervous system following acute spinal cord injury (SCI), traumatic brain injury, acute ischemic stroke (AIS), and other neuropathological conditions." (PMID 37326791, 2024).
Cognitive impairment (1 paper, 2025). Abnormal cognition is characterized by deficits in thinking, reasoning, or remembering. "In the present study, we provide new insights into the molecular pathology in the hippocampus of a mouse model of VaD and propose anti-RGMa treatment as a novel therapeutic strategy to counteract cognitive impairment associated with VaD." (PMID 39613526, 2025). "Furthermore, we obtained evidence that RGMa is involved in hippocampal pathology, and the suppression of RGMa signaling effectively ameliorated BCAS-induced cognitive impairment." (PMID 39613526, 2025). "Together, we speculated that the anti-RGMa neutralizing antibody attenuated BCAS-induced cognitive impairment by improving cholinergic innervation disturbance as well as neurogenesis impairment." (PMID 39613526, 2025).
colorectal cancer (1 paper, 2023). A primary or metastatic malignant neoplasm that affects the colon or rectum. "In a study of colorectal cancer, it was found that overexpression of RGMA inhibited the proliferation, migration and invasion of tumor cells, and increased cell apoptosis, which can be used as an important marker for early diagnosis and prognosis of tumors." (PMID 37308925, 2023).
developmental delay (1 paper, 2014). "However, because of the importance of RGMA in central nervous system axonal growth, haploinsufficiency of this gene was thought to be a good candidate to explain the patient’s developmental delay and seizures." (PMID 24834135, 2014).
gastric cancer (1 paper, 2014). A primary or metastatic malignant neoplasm involving the stomach. "Neogenin-1 ligands netrin-1 and RGMa were expressed at low levels or not at all in gastric cancer cells, respectively." (PMID 24930499, 2014).
glaucoma (1 paper, 2021). Increased pressure in the eyeball due to obstruction of the outflow of aqueous humor. "It is only upregulated in CAβ3 cells (FC = 2.16), and elevated RGMA expression has been associated with glaucoma in mice." (PMID 34440692, 2021).
Hepatitis (1 paper, 2025). Inflammation of the liver. "Four interesting SNPs possibly associated with ICI-induced hepatitis were identified in our tumour specimens: three of them, GABRP rs11743438, GABRP rs11743735, and PACRG rs55733913 were found linked to a higher risk of hepatitis, while RGMA rs4778080 seemed to protect against this adverse event." (PMID 41153639, 2025).
lymphopenia (1 paper, 2019). Reduction in the number of lymphocytes. "The observation of lymphopenia in EBOV/Makona-rgMA-infected mice that coincided with EBOV/Mayinga-MA-infected mice shows the ability of EBOV/Makona-rgMA to recapitulate characteristics of EVD in mice." (PMID 31717793, 2019).
opioid dependence (1 paper, 2020). "A recent analysis on 4 different populations with thousands of patients identified a variant on chromosome 15, rs12442183, near RGMA, associated with opioid dependence (p = 1.3 × 10−8)." (PMID 32708424, 2020).
oral squamous cell carcinoma (1 paper, 2020). "Previous studies have found that RGMA inhibits the proliferation of oral squamous cell carcinoma (OSCC) cells, and the low expression of RGMA is closely related to the poor prognosis of patients with OSCC." (PMID 32650755, 2020).